ATM (ATM serine/threonine kinase)
Diseases named in the same sentence as ATM in open-access papers (continued):
Sharing a sentence is not in itself a finding about the gene and the disease.
pancreatic cancer (continued). "For PALB2 and ATM carriers, pancreatic cancer screening can be considered starting at age 50 or earlier if there is a relevant family history." (PMID 40649708, 2025). "In accordance with this tumour suppressor status, deletion of ATM in mice accelerates RAS-driven pancreatic cancer development and metastasis." (PMID 40723241, 2025). "It was agreed that pancreatic cancer screening advice should be given at the time of diagnosis for individuals with a GPV in ATM." (PMID 41159931, 2025). "After curcumin treatment in BXPC‐3 human pancreatic cancer cells, cell cycle arrest was observed at the G2/M phase, which also induced apoptosis through ATM/Chk1." (PMID 41179371, 2025). "In immunocompetent syngeneic mouse models of pancreatic cancer, ATM inhibitor enhanced radiation-induced antitumoral immune responses and sensitized tumors to anti–PD-L1, producing immunogenic memory and durable tumor control." (PMID 38376927, 2024). "In cells harboring ATM mutations, PARPi or ATR inhibitors enhanced the apoptosis rate of pancreatic cancer and subsequently increased synthetic lethality." (PMID 38184614, 2024). "Our data herein demonstrate compelling efficacy of ATM inhibitor in enhancing radiation-induced antitumor immune responses in pancreatic cancer." (PMID 38376927, 2024). "In this study, we showed that the ATM inhibitor AZD1390 in combination with radiation can induce T1IFN-mediated antitumoral immune responses in otherwise immunologically suppressed pancreatic cancer." (PMID 38376927, 2024). "Therapeutic targeting of ATM in combination with radiotherapy induces an antitumoral immune response and sensitizes tumors to anti–PD-L1 immunotherapy in pancreatic cancer." (PMID 38376927, 2024). "Overall, this study forms the foundation for future clinical investigations combining ATM inhibitors with radiation and immunotherapy with the goal of improving both local and systemic disease management in patients with pancreatic cancer." (PMID 38376927, 2024). "An additional study of AZD6738 investigates solid tumors (including pancreatic cancer) and determines response rates to therapy with ATR kinase inhibitor monotherapy and in combination with olaparib in an ATM loss and an ARID1A mutated subgroup (NCT03682289)." (PMID 38184614, 2024). "PTVs in ATM and CHEK2 are associated with a wide range of cancers, with the highest RR for pancreatic cancer in ATM PTV carriers." (PMID 39209703, 2024). "Most familial pancreatic cancer is attributable to hereditary breast and ovarian cancer syndrome that results from germline mutations in BRCA1/2 genes and other genes such as ATM, BRIP1, CHEK2, RAD50, and RAD51C." (PMID 38732320, 2024). "Here, we extend the POLQ-HR synthetic lethal interaction to pancreatic cancer cells and report a synthetic lethal interaction between ATM and POLQ." (PMID 36976649, 2023). "Loss of expression of the gene ataxia-telangiectasia mutated (ATM), occurring in patients with multiple primary malignancies, including pancreatic cancer, is associated with poor prognosis." (PMID 37674118, 2023). "The second most commonly mutated DDR gene after BRCA2 was ATM, with 5 mutated cases in the MSK-IMPACT pancreatic cancer cohort." (PMID 36975505, 2023).
pancreatic cancer (continued). "As discussed in a previous section, besides BRCA1 and BRCA2 mutations, mutations in PALB2, ATM, ATR, BRIP1, BARD1 and CDK12 are observed in low frequencies in pancreatic cancers." (PMID 36975505, 2023). "In this study, we investigated the detailed molecular mechanism through which ATM expression affects the prognosis of patients with pancreatic cancer." (PMID 37674118, 2023). "The levels of expression of ATM and phosphorylated ATM in patients with pancreatic cancer who had undergone surgical resection were analyzed using immunohistochemistry staining." (PMID 37674118, 2023). "ATM deficiency markedly increases the proportion of chromosomal alterations in pancreatic primary tumors with KRASG12D and renders pancreatic tumors highly sensitive to radiation in association with increased residual DSB 24 h post-4 Gy." (PMID 36313934, 2023). "Pancreatic cancer that occurred among first-degree relatives of two of our seven identified HBOC patients, is known to be associated with pathogenic ATM variants." (PMID 40225144, 2023). "WEE1 inhibitor adavosertib (AZD1775) synergizes with ATM inhibitor AZD0156 in reducing proliferation of pancreatic cancer cells." (PMID 36975505, 2023). "For the combination of BC and pancreatic cancer (n = 175), PVs were most frequent in ATM (6.9%, 95% CI 4.0–11.6%) followed by BRCA2 (5.1%, 95% CI 2.5–9.8%)." (PMID 36856935, 2023). "The prevalence of PVs in ATM among females with BC and pancreatic cancer was greater than the prevalence of BRCA2 PVs." (PMID 36856935, 2023). "Patients with KRAS wild‐type disease and early‐onset pancreatic cancer (EOPC) harbored actionable mutations including BRAF, EGFR, ERBB2, and MAP2K1/2.PGVs in PALB2, BRCA2, and ATM were associated with high PDAC risk in the Chinese population." (PMID 36999792, 2023). "Low expression of phosphorylated ATM substantially reduced overall and disease-free survival in patients with pancreatic cancer." (PMID 37674118, 2023). "In the pancreatic cancer cell lines with ATM low expression, resistance to gemcitabine was demonstrated." (PMID 37674118, 2023). "Overall, these results indicate that the efficacy of ICI in pancreatic cancer is enhanced by ATM inhibition and further enhanced by IR, depending on the increased immunogenicity of the tumor." (PMID 37420037, 2023). "Inhibition of WEE1 has synergistic effects with ATM inhibitors in pancreatic cancer preclinical models in vitro and in vivo." (PMID 36975505, 2023). "The authors also found that low ATM expression inversely correlated with PD-L1 expression in patients’ pancreatic tumors." (PMID 37420037, 2023). "In patients with a family history, ATM germline PVs were identified in 2.6% of pancreatic cancer cases." (PMID 35008949, 2022). "In a case series on pancreatic ductal adenocarcinoma, 8 out of 10 pancreatic cancer patients with ATM, ATR, or CHEK2 GPVs were treated with an oxaliplatin-based chemotherapy regimen and 5 patients demonstrated a partial response or stable disease." (PMID 35806485, 2022). "Over the last decade, the genetics associated with pancreatic cancer has been intricately assessed Some well-known cancer gene germline mutations have been identified in patients with pancreatic cancer, including BRCA1/2, PALB2, STK11, PRSS1, SPINK1 and ATM." (PMID 35813042, 2022). "Most familial pancreatic cancer (FPC) is attributable to HBOC syndrome that results from germline mutations in BRCA1/2 genes and other genes such as ATM, BRIP1, CHEK2, RAD50, and RAD51C." (PMID 35205366, 2022). "Further studies revealed that ALDOA expression positively correlates with PLK1 expression and negatively correlates with ATM expression in pancreatic cancer patients." (PMID 34565365, 2021).
pancreatic cancer (continued). "We identified alterations associated with HRD, including mutations in ATM and ATR genes; specific deletions in stomach, bladder, and lung cancer; and BRCA-wild type breast, ovarian, and pancreatic cancers." (PMID 34572800, 2021). "An ongoing trial assessing an oral ATR inhibitor in combination with olaparib for advanced solid tumors (including ATM mutant pancreatic cancer) will be informative (ClinicalTrials.gov Identifier: NCT03682289)." (PMID 34572943, 2021). "In the actual test results, nearly half of the pancreatic cancer patients with ATM alterations had changes in the m1A regulatory gene." (PMID 33779693, 2021). "Similar results were seen with the pancreatic cancer cell line, Panc 10.05, in which ATM was depleted by shRNA." (PMID 32183301, 2020). "We demonstrate that IPMNs and MCNs are precursors of invasive pancreatic cancer, that alterations in ATM, GLI3, and SF3B1 are present in these lesions, and that SMAD4/TGFBR2 alterations are likely drivers of invasion in a subset of cases." (PMID 32796935, 2020). "Recently, Zhang and colleagues have demonstrated that inhibition of ATM increases interferon signaling and sensitizes pancreatic cancer to immune checkpoint inhibition." (PMID 33224881, 2020). "Although over 80% of familial pancreatic cancer cases harbor mutations in BRCA1/2 and ATM, germline deletion and mutations of BAP1 have also been observed." (PMID 32541668, 2020). "Further GO and signaling pathway analyses showed that the predicted targets of these miRNAs mainly focused on DNA binding, mitosis, integrated pancreatic cancer pathway, DNA damage response only ATM dependent, insulin signaling, and type II diabetes mellitus." (PMID 31993806, 2020). "A number of studies have shown that pedigrees with germline mutations in ATM, BRCA1, and BRCA2 also have an increased lifetime risk of pancreatic cancer in familial pancreatic cancer (FPC) kindreds." (PMID 31480737, 2019). "These and other results postulate that ATM activity poses a barrier to pancreatic cancer progression via maintaining chromosome stability." (PMID 28894253, 2017). "Third, we show that ATM activity is necessary in established pancreatic tumors to prevent the accumulation of deleterious DNA lesions and to preserve genome integrity." (PMID 28894253, 2017). "In this study, we demonstrated that HS-173 is a potent inhibitor of PI3K/AKT signaling that responds to radiation-induced DNA breaks and repair by inhibiting ATM and DNA-PKcs, resulting in profound radiosensitization in pancreatic cancer cells." (PMID 29348875, 2017). "Among 190 pancreatic cancer patients, the positive yield was 10.5% (n = 20), and positive results were most commonly identified in ATM (40.0%; 8/20), BRCA2 (25.0%; 5/20), and PALB2 (15.0%; 3/20)." (PMID 26681312, 2016).
pancreatic cancer (continued). "Our data suggest an intimate link between ATM expression and pancreatic cancer progression in mice and men." (PMID 26220524, 2015). "Paradoxically, upregulation of ATM in prostate and pancreatic cancer cells has been frequently reported, linking this condition to those cells that have somehow escaped cell-cycle arrest and apoptosis." (PMID 25247188, 2014). "ATM and PALB2 variants were recently associated with familial pancreatic cancer (FPC) using exome sequencing (ES)." (PMID 23561644, 2013). "This study reflects the critical role of ATM/Chk1 in curcumin-mediated G2/M cell cycle arrest and apoptosis in pancreatic cancer cells." (PMID 19401701, 2009). "PER1 combats pancreatic cancer by activating the ATM signaling pathway." (PMID 39791162, 2025). "The estimated absolute risks for pancreatic cancer in ATM PTV carriers (11% in males and 8% in females by age 85) are notably higher than for other major pancreatic susceptibility genes including BRCA2, CDK2NA, and PALB2, although the confidence limits are wide." (PMID 39209703, 2024). "Furthermore, ATM inhibition was reported to activate TBK1 in a cGAS-STING-independent manner via SRC kinase in pancreatic cancer cells." (PMID 38084916, 2024). "However, another tumor-agnostic phase 2 study showed no significant anticancer activity of olaparib in somatic or germline ATM- or CHEK2-mutated cancers, although only four patients with pancreatic cancer were enrolled." (PMID 39456541, 2024). "Interestingly, there are some data supporting that ATM variant carriers diagnosed with pancreatic ductal adenocarcinoma could have longer survival, and both ATM variants here identified were found in two long responding patients diagnosed with melanoma and pancreatic cancer, respectively." (PMID 38750555, 2024). "CAPS recommends pancreatic cancer screening beginning at the age of 50 years or 5 years earlier than for high-risk individuals with defined familial pancreatic cancer in patients with BRCA2, ATM, and PALB2 mutations (Grade 2: probably do it)." (PMID 39200847, 2024). "ATM p.S978P has been reported to have implications in pancreatic cancer." (PMID 38784039, 2024). "Furthermore, we found that purified His-hAPE1 protein stimulated robust ATM phosphorylation in a dose-dependent manner in an in vitro ATM DDR activation system using nuclear extracts isolated from human pancreatic cancer PANC1 cells." (PMID 39112456, 2024). "In addition, silencing of ATM increased PD-L1 expression and enhanced the sensitivity of pancreatic tumors to PD-L1-blocking antibodies." (PMID 37420037, 2023). "Furthermore, in another family with 10 healthy collateral relatives of a proband with pancreatic cancer at the age of 58 years, we tested two variants: BRCA2 c.8487+1G>A and ATM c.6095G>A." (PMID 38136276, 2023). "Nevertheless, a systematic examination of ATR inhibitors and combinations with chemotherapy or PARP inhibitors specifically in pancreatic cancer patients with ATM mutations has not been performed and needs to be investigated prospectively in a clinical trial." (PMID 36975505, 2023). "The key function of K-Ras in this interaction is also supported by the enhanced sensitivity of KRAS-mutant lung cancer cells to MEK inhibition after ATM loss and radiosensitization of KRAS-mutated pancreatic cancer cells after MEK targeting through inhibition of HR- and NHEJ-dependent DSB repair." (PMID 36313934, 2023). "In addition, biallelic ATM inactivation has been found with a higher frequency in PDAC specimens from familial pancreatic cancer patients compared to sporadic cases." (PMID 38201484, 2023).
pancreatic cancer (continued). "The risk for pancreatic cancer in individuals with pathogenic variants of BRCA1, BRCA2, PALB2, or ATM but without a history of pancreatic cancer has not been elucidated." (PMID 35163129, 2022). "Furthermore, ATM silencing increased PD-L1 expression, tumoral CD8 cells, and the sensitivity of pancreatic tumors to ICIs, suggesting that the efficacy of ICIs in pancreatic cancer can be enhanced by ATM inhibition." (PMID 35572596, 2022). "ATM reduction could therefore contribute to the increase in DNA damage observed in pancreatic cancer cells following c-Myc inhibition." (PMID 36289751, 2022). "In addition, TRIM29 is phosphorylated by MAPKAP kinase 2 (MK2) at Ser550 in an ATM-dependent manner and performs a radioprotective function in pancreatic cancer cells." (PMID 35054873, 2022). "We speculate that m1A-regulating genes may induce the activation of ATM signaling pathway in the progression of pancreatic cancer." (PMID 33779693, 2021). "Next, we administered phospho-PLK1-T210 to determine whether ATM inhibits PLK1 activation in human pancreatic cancer cells." (PMID 34565365, 2021). "Evidence supports that risk for pancreatic cancer may be elevated as well in those with a pathogenic ATM variant, and BRCA1 is a downstream target of the ATM gene." (PMID 32793315, 2020). "In a prospective multicenter study to characterize pathogenic germline variants in pancreatic cancer susceptibility genes in 298 unselected patients with PDAC by Brand and colleagues, pathogenic germline ATM variants were observed in 10 patients (3.3%) in the most frequently encountered gene." (PMID 31963441, 2020). "Moreover, in one patient with available pancreatic tumor tissue, loss-of-heterozygosity (LOH) at the ATM locus was demonstrated with retention of the nonsense variant, demonstrating that ATM conformed to the classic two-hit model for tumor suppressor genes." (PMID 31963441, 2020). "They identified pathogenic germline ATM variants in 10 patients (1.2%), indicating that ATM plays a previously unappreciated role in susceptibility to pancreatic cancer even in patients without a family history of the disease." (PMID 31963441, 2020). "In conclusion, our combined qPCR results indicate that while ATM deficiency accelerates pancreatic cancer formation it does not confer a specific phenotype/genotype to pancreatic tumors." (PMID 28894253, 2017). "Second, we establish that lack of ATM causes persistent DNA damage in pancreatic tumors of mice and possibly also in pancreatic tumors of humans." (PMID 28894253, 2017). "However, those authors did not report chromosomal alterations or excessive DNA damage in pancreatic tumors that lack ATM." (PMID 28894253, 2017). "Thus, it is conceivable that ATM signaling is activated in pancreatic tumors of mice and humans to prevent the propagation of unrepaired DNA damage and to preserve genome integrity." (PMID 28894253, 2017). "Loss of ATM was discovered significantly more often in patients with a family history of pancreatic cancer (12/49; 24.5%) than in those without (38/347; 11.0%)." (PMID 29069866, 2017). "Possible synthetic lethal interactions may be produced in patients with pancreatic cancer using the new targeted therapies, ATM or ATR inhibitors, as ATM and ATR are key participants in DNA repair." (PMID 29069866, 2017). "To date, the role of ATM in pancreatic cancer initiation/progression is largely unclear." (PMID 26220524, 2015). "Finally, we applied the BMP4 signalling signature used in our mouse model to stratify pancreatic cancer patients, which have been separated according to their ATM expression levels (high vs low)." (PMID 26220524, 2015). "To conclude, our present observations state that curcumin treatment potentially inhibits the proliferation of BxPC-3 human pancreatic cancer cells by DNA damage-mediated G2/M cell cycle arrest by the activation of ATM/Chk1/Cdc25C and inhibition of cyclin B1/Cdk1 expression." (PMID 19401701, 2009).